CDK6 (cyclin dependent kinase 6)
Diseases named in the same sentence as CDK6 in open-access papers (continued):
Sharing a sentence is not in itself a finding about the gene and the disease.
cancer (continued). "More recently, transcriptome analyses performed in different cancer cell models modified for CDK4 and CDK6 expression or activity, highlighted that, beyond the control of the G1 phase of the cell cycle, CDK4 and CDK6 might play non-cell cycle related functions via the regulation of transcription." (PMID 34204543, 2021). "Thus, the bioactive compounds from FA and their interactions with PTGS2, HSP90, CDK6, caspase 3, Bcl-2, and MMP9 may be key in the treatment of cardiovascular disease and various cancers." (PMID 33542744, 2021). "Among, 10953 patients/10967 samples of all type of human cancers publicly available in the online cancer genomic database cBioPortal, genetic alterations of CDK2/4/6 and STAT3 occurs in 825 (8%) patients, comprising 127 (1.2%) CDK2, 307 (2.8%) CDK4, 266 (2.4%) CDK6, and 220 (2%) STAT3 and." (PMID 33668805, 2021). "In addition, FDA-approved CDK4/CDK6 inhibitors, including ribociclib, abemaciclib, and palbociclib, as well as other CDK antagonists, are presently in clinical trials as single agents or combined with other drugs for various cancer types." (PMID 34361615, 2021). "Collectively, our findings supports the hypothesis that activation of the ATM/AKT/GSK-3β signaling pathway leading to CDK4/CDK6/cyclin D1 overexpression plays a key role in LDR-induced hormesis, and is responsible for the difference of hormesis induced by LDR in normal and cancer cells." (PMID 27708248, 2016). "Moreover, the functions of CDK1/cyclin B1 in human cancer had not been properly elucidated similar to CDK4/CDK6/cyclin D. Multi-CDK inhibitors that target CDK1 are well-tolerated in cancer patients." (PMID 25914884, 2015). "Deregulation of Cdk4 is widespread in human cancer, CDK4 gene knockout is highly protective against chemical and oncogene-mediated epithelial carcinogenesis, despite the continued presence of CDK2 and CDK6; and overexpresssion of Cdk4 promotes skin carcinogenesis." (PMID 21668989, 2011). "Importantly, this study demonstrated that CDK6 is a novel multi-functional target that may act as an on-off switch for ABCB1 expression, potentially reversing ABCB1-mediated MDR in cancers, and therefore, has significance in combination with cancer chemotherapy." (PMID 35459184, 2022). "Predictably, due to its ubiquitous expression across a large number of tissues, CDK6 is not shown to be overexpressed in the brain, possibly suggesting that its relationship to Intellectual Disability is not as significant compared to other diseases, most of which are cancer." (PMID 32858868, 2020). "A requirement for the FPPRGPRPVQSV region of Cdk4 to provide energy for cancer cell division could also provide an explanation for the fact that Cdk4 rather than Cdk2 or Cdk6 appears to be the mandatory cyclin-dependent kinase for carcinogenic malignant transformation." (PMID 21668989, 2011). "Interestingly, our results showed that the expression levels of CDK4, CDK6, and cyclin D1 in CRC cells were visually reduced after POLQ knockdown, which suggested that POLQ knockdown affects the cell cycle process and may be a potential factor in cancer therapy." (PMID 39520627, 2024). "Recently, there have been studies on CDK4 and CDK6, but the mechanism of CDK2 in cancer is relatively lacking." (PMID 34409029, 2021). "The results showed that knockdown of CDK6 but not CDK4 reduced RB phosphorylation and inhibited carcinoma cell growth." (PMID 24765199, 2014). "We identified new gene fusions involving ROS1, SLC1A2, RAF1, EWSR1, CDK6, and CLTC, some occurring in cancer types not previously known to harbor fusions." (PMID 23637631, 2013). "After screening a panel of human cancer cell lines for CDK4 and CDK6 expression (data not shown), the U20S cell line was selected, as it accumulated approximately threefold higher levels of CDK6 compared to the WMM1175 cell line." (PMID 18843795, 2008).
cancer (continued). "Together, we unveil CDK6 as a druggable target in lenvatinib-resistant HCC and highlight the use of a chemical biology approach to understand nongenetic resistance mechanisms in cancer." (PMID 37872167, 2023). "While we similarly note increased CDK6 expression in our ESR1-mutant models, this did not confer diminished elacestrant antagonism, possibly due to alternate primary resistance mechanisms driving the growth of the cancer cells in our models." (PMID 31852484, 2019). "Furthermore, cyclin D1 (CCND1), CDK1 and CDK6 mRNA levels were significantly higher in CRC compared to normal children samples, which may be related to the uncontrolled cellular proliferation in cancer." (PMID 24098334, 2013).
infection (17 papers, 2009 to 2025). The state of being infected such as from the introduction of a foreign agent such as serum, vaccine, antigenic substance or organism. "CDK6 is required for NETosis, as a previous study has reported mice with CDK6-deficiency are more susceptible to infection." (PMID 39300084, 2024). "The other BCL-2 family gene upregulated during infection is CDK6, which facilitates cell cycle progression and is associated with c-MYC-induced cell proliferation and hence could counteract apoptosis." (PMID 39976440, 2025). "In the current investigation, it was observed that the expression of CDK4 was reduced while CDK6 expression was increased following LPS infection." (PMID 40136393, 2025). "The genes specifically downregulated over the course of infection by Fasciola miRNAs included Nod1, E2f1, Tnfaip3 and Cdk6 at 6 hrs, and Jam3, Vegfa, Nod1, Uvrag and Nlrc3 at 18 hrs." (PMID 39344634, 2024). "Among these factors, the cell cycle regulators aurora kinase B (AURKB) and cyclin-dependent kinase 6 (CDK6) were shown to be resistance factors restricting EV-A71 infection, with the nuclear egress of CDK6 regulated by EV-A71." (PMID 33381104, 2020). "We found that Lv-CDK6 infection reversed the attenuation of mechanical allodynia and thermal hyperalgesia by Lv-shPKIA-AS1 infection following SNL." (PMID 30873006, 2019). "The methylation status of CDK6 promoter was evaluated by quantitative methylation-specific PCR (qMSP) of the PC12 cells following Lv-PKIA-AS1 infection." (PMID 30873006, 2019). "Compared with lenti-ctrl infection, lenti-CDK6 infection significantly increased CDK6 protein level." (PMID 26542173, 2015). "As expected, re-infection with lenti-CDK6 alleviated the down-regulation of CDK6 expression resulted from lenti-ZFP36L1 treatment (iv versus ii)." (PMID 26542173, 2015). "We further demonstrated that Lv-PKIA-AS1 infection upregulated CDK6 gene promotor activity." (PMID 30873006, 2019). "Indeed, Lv-PKIA-AS1 infection induced CDK6 overexpression at both mRNA and protein levels." (PMID 30873006, 2019). "In addition, PKIA-AS1 knockdown-mediated inhibition of CDK6 was reversed by Lv-CDK6 infection." (PMID 30873006, 2019). "In our study, the expression of cyclin-dependent kinase inhibitor 1B (CDN1B), cyclin-dependent kinase 6 (CDK6) and cyclin-dependent kinase 1 isoform 1 (CDK1) was found to be downregulated during aMPV/C infection in Vero cells." (PMID 32231136, 2020). "Compared with lenti-ctrl infection, lenti-ZFP36L1 and lenti-shZFP36L1 infection significantly increased and decreased ZFP36L1 protein level respectively, which led to the remarkable down-regulation and up-regulation of CDK6 expression respectively." (PMID 26542173, 2015). "Taken together, the results indicate that v-cyclin phosphorylates NPM on Thr199 by activating CDK6 in the KSHV-infected endothelial and BC-3 cells, which are both biologically relevant cell types in KSHV-infections and malignancies." (PMID 20333249, 2010). "Infection with rKSHV.219 induced prominent phosphorylation of NPM on threonine 199 in both cell lines, which interestingly, was accompanied by an increase in CDK6 protein levels." (PMID 20333249, 2010). "For example, CycD, CDK4 and CDK6, were upregulated in HIGK infected with the mixed microflora compared to HIGK transcript levels in response to mono-infection with P. gingivalis." (PMID 19689803, 2009). "We demonstrated that cyclinD, CDK4, CDK6, cyclinE1 and CDK2 are down-regulated after EV-D68 infection, which could explain the ability of EV-D68 to inhibit the transition from G0/G1 to S phase." (PMID 28229049, 2017). "Kinases with pro-latency roles include CDK6 which interacts with KSHV v-cyclin and nucleophosmin to restrict lytic replication, and AMPKα1 which restricts lytic replication following primary infection through an unknown mechanism." (PMID 37669313, 2023).
infection (continued). "We investigated the impact of the MAPK family inhibitors Selumetinib (MEK1 and MEK2) and JNK-IN-8 (JNK family), and the impact of CDK family kinase inhibitors Roscovitine (CDK2, CDK5), Dinaciclib (CDK4, CDK6), and the non-specific CDK/Crk during infection (Fig. EV2A,B)." (PMID 38177504, 2024).
hematological malignancies (10 papers, 2009 to 2025). "CDK4/CDK6 is a well-established target in applied oncology and has also been discussed in the context of hematologic malignancies." (PMID 35804842, 2022). "More recent pre-clinical studies have shown promising effects of CDK4/CDK6 inhibitors in certain hematologic malignancies." (PMID 35804842, 2022). "Altogether, these studies suggest that in hematological malignancies, CDK6 has an important role in the regulation of cell proliferation." (PMID 34573335, 2021). "As CDK6 is frequently overexpressed in hematologic malignancies, inhibition of CDK6 appears a promising treatment option and numerous clinical studies are underway." (PMID 33255177, 2020). "Alterations for CDK6 include overexpression, which is frequently found in hematologic malignancies." (PMID 33255177, 2020). "While there are no inhibitors that directly target cyclin D, alternative therapeutic strategies targeting CDK4/CDK6 could be potentially useful in hematologic malignancies with altered D-type cyclins." (PMID 25914884, 2015). "CDK6 is a key regulator of several AML subtypes, making it a favourable therapeutic target for this aggressive haematologic disease." (PMID 35326705, 2022). "In combination with other agents, CDK6-selective PROTACs may be valuable components of chemotherapy-free protocols for the therapy of Ph+ ALL and other CDK6-dependent hematological malignancies." (PMID 34573335, 2021).
hematopoietic cancer (5 papers, 2011 to 2022). "CDK6 also plays a crucial role in malignant hematopoietic tumors." (PMID 33597968, 2020). "To determine whether CDK6 is a common essential effector of oncogenic tyrosine kinases, we evaluated its contribution downstream of oncogenic KIT, a receptor closely related to FLT3 also involved in hematopoietic neoplasms." (PMID 27323399, 2016).
cardiovascular disease (3 papers, 2013 to 2021). "The downregulation of CDK6 was necessary to demonstrate remarkably deteriorating cardiovascular disease risk by destroying the vascular endothelial structure and function." (PMID 33224271, 2020).
colon (3 papers, 2014 to 2021). "Interestingly, the downregulated DEGs, such as MAD2L1, CCNA2, MCM2, MCM4, FEN1, and CDK6, were enriched in DNA replication, tyrosine metabolism, and cell cycle pathways, which are commonly upregulated in colon cancer." (PMID 34521988, 2021). "Overall these results suggested that CDK6 overexpression allows mouse GI tumors to grow outside the colonic sub-mucosal environment and that activation of CDK6 might contribute to GI tumors surviving and thriving in a metastatic setting." (PMID 25162504, 2014).
benign tumors (1 paper, 2015). "Somewhat unexpectedly, Cdk6 mRNA expression was increased in arrested benign tumors." (PMID 25900242, 2015).
CNS tumours (1 paper, 2024). "Adult CNS tumours have high CDK6 amplification, 10q loss, and 17q gain, whereas paediatric cases have a high frequency and high specificity of 3q and 4q losses across MYC/MYCN oncogene amplification, suggesting variations in the chromosomal abnormalities between adult and paediatric CNS tumours." (PMID 39439908, 2024).
colorectal (1 paper, 2019). "Our results suggest three intracellular protein targets CDK6, PIM1 and MAPK/p38 that have been reported to play an important role in colorectal carcinogenesis." (PMID 30655588, 2019).
vasculopathy (1 paper, 2020). "Thus, our identified DEGs (RRM2, APC, CHEK1, E2F6, TYMS, E2F7, and CDK6) from the cluster 2 subnetwork are highly related to and consistent with the members of the signaling pathways associated with the immune system, apoptosis, the cell cycle, and vasculopathy." (PMID 32426333, 2020).
CDK6 also shares sentences with these, for which no sentence is quoted: adenocarcinoma (3 papers); cutaneous melanoma (3); metabolic disease (3); metabolic syndrome (3); autosomal recessive primary microcephaly (2); colorectal tumor (2); ependymoma (2); ischemia (2); laryngeal squamous cell carcinoma (2); leukopenia (2); low grade glioma (2); myxofibrosarcoma (2); neurodegenerative disease (2); pancreatic adenocarcinoma (2); pancreatic endocrine tumors (2); splenic marginal zone lymphoma (2); tongue squamous cell carcinoma (2); acral melanoma (1); adult T-cell leukemia/lymphoma (1); Allergy (1); alveolar rhabdomyosarcoma (1); anaplastic astrocytoma (1); angina (1); angiosarcoma (1); arteriovenous malformations (1); Azoospermia (1); basal cell carcinoma (1); bile duct cancer (1); blastoma (1); bone cancer (1).
A further 62 diseases each share a sentence with CDK6 in 1 paper.